TXNIP (thioredoxin interacting protein)
Diseases named in the same sentence as TXNIP in open-access papers (continued):
Sharing a sentence is not in itself a finding about the gene and the disease.
type 2 diabetes (continued). "Patients with BD are three times more likely to be diagnosed with type II diabetes compared to the general population, suggesting that NLRP3 inflammasome activation mediated by TXNIP could be underlying increased peripheral and CNS inflammation in patients with BD." (PMID 26075098, 2015). "Similarly, a methylation score based on five markers located in ABCG1, PHOSPHO1, SOCS3, SREBF1, and TXNIP could predict future type 2 diabetes incidence independent of established risk factors." (PMID 35159278, 2022). "ER stress-related TXNIP/NLRP3 inflammasome activation is involved in the pathophysiology of SAH, neonatal hypoxic-ischemic brain injury, type 2 diabetes, and many other diseases." (PMID 36171629, 2022). "Studies on type II diabetes mellitus, acute kidney injury, hepatocyte injury, preeclampsia, and other diseases have shown that ERS can regulate pyroptosis through the TXNIP/NLRP3 pathway." (PMID 36552271, 2022). "TXNIP activates the NLRP3 inflammasome and subsequent secretion of IL-1β in the pathogenesis of type 2 diabetes." (PMID 32842536, 2020). "In this study, we investigated the relationship between serum TXNIP levels and NCV in patients with type 2 diabetes to provide a new target for the prevention and treatment of DPN." (PMID 32774321, 2020). "A family-based study of 859 Mexican Americans showed that the degree of methylation at top regions including TXNIP, ABCG1 and SAMD12 genes and two intragenic regions accounted for 7.8% of the heritability of type 2 diabetes in Mexican Americans." (PMID 29164275, 2018). "The axis of TXNIP and NLRP3 inflammasome has been confirmed to be an important player in CNS dysfunction or several diseases, such as hippocampus injury, type 2 diabetes, and brain ischemic stroke." (PMID 29386025, 2018). "In leucocytes from patients with type 2 diabetes, the TXNIP mRNA level was significantly correlated with OGA, but not with OGT mRNA." (PMID 35887161, 2022). "Recent epigenome-wide association studies (EWASs) in blood have identified differentially methylated CpG sites (DMS), in individuals with vs without type 2 diabetes, in genes such as TXNIP, ABCG1 and SREBF1." (PMID 35169870, 2022). "TXNIP is a critical signalling protein that mediates inflammation and pancreatic β cell death, while NLRP3 inflammasome is responsible for the trigger of islet inflammation in type 2 diabetes." (PMID 36079752, 2022). "Interestingly, the thioredoxin interacting protein (TXNIP), which inhibits the antioxidative action of thioredoxin and is elevated upon ER stress and insulin misfolding, was also found to be elevated in type 2 diabetes islets." (PMID 32894308, 2020). "One research of type 2 diabetes has shown that the maturation of caspase-1 and IL-1β, the sign of NLRP3 inflammation activation, did not required TXNIP in bone marrow-derived macrophages." (PMID 25136835, 2014).
Insulin resistance (48 papers, 2012 to 2025). Increased resistance towards insulin, that is, diminished effectiveness of insulin in reducing blood glucose levels. "Thioredoxin-interacting protein (TXNIP), a protein associated with insulin resistance, also plays a role in NLRP3 inflammasome activation." (PMID 40433411, 2025). "Animal studies show that TXNIP overexpression leads to β-cell apoptosis and impaired insulin sensitivity, while TXNIP deficiency protects against diet-induced insulin resistance and T2DM." (PMID 40648980, 2025). "In resting cells, thioredoxin-interacting protein (TXNIP), a protein linked to insulin resistance, TXNIP interacts with thioredoxin." (PMID 36506093, 2022). "Higher serum TXNIP was also indicated to be associated with impaired β cell function and insulin resistance in PCOS patients." (PMID 33224973, 2020). "Our major findings were: (i) The high mRNA levels of TXNIP in bone from CS patients were significantly associated with high levels of glucose and insulin, increased insulin resistance, and decreased insulin sensitivity in these patients." (PMID 23691179, 2013). "This was investigated in vivo by looking at associations between TRX/TXNIP, OC and indices of insulin resistance and in vitro by modulating TXNIP in osteoblasts and investigating effects of these osteoblasts on pancreatic islets." (PMID 23691179, 2013). "In contrast, animals with TXNIP deficiency are immune to diet-induced insulin resistance and T2DM." (PMID 35571083, 2022). "Decreases in Mondo A/Mlx/G6P transcriptional activity are also expected to decrease the expression of other ChRE-linked genes—TXNIP, lipogenic enzymes, and others —which may improve glucose tolerance and decrease insulin resistance." (PMID 35216280, 2022). "Moreover, health improvement was linked to two established mediators of insulin resistance: TXNIP and TNFα." (PMID 34371884, 2021). "These markers located in ABCG1, PHOSPHO1, SOCS3, SREBF1, and TXNIP were associated with metabolic measures of insulin resistance including glucose concentration, BMI, waist-to-hip ratio, and homeostatic model assessment for insulin resistance (HOMA-IR)." (PMID 32211026, 2020). "Similarly, research reveals that ROS can liberate TXNIP (thioredoxin-interacting protein), a protein linked to insulin resistance, which then interacts with NLRP3 and stimulates inflammasome assembly." (PMID 32927712, 2020). "The third paradigm, gene silencing, targets pathogenic players in insulin resistance or β-cell apoptosis (e.g., PTP1B, TXNIP) using siRNA or shRNA." (PMID 41226304, 2025). "There were also links to two established mediators of insulin resistance: TXNIP and tumor necrosis factor-α (TNFα)." (PMID 38292764, 2023). "TXNIP is a mediator of insulin resistance in the liver, skeletal muscle, and adipose tissue and impaired pancreatic beta-cell insulin secretion." (PMID 38292764, 2023). "Thioredoxin interacting protein (TXNIP) is an aspiring target of miRNA-17-5p which was described in metabolic disorders including obesity and insulin resistance." (PMID 37547923, 2023). "TXNIP expression is drastically upregulated by elevated blood glucose levels and promotes insulin resistance through the inhibition of glucose uptake." (PMID 39319322, 2023). "Recent studies have found that verapamil can inhibit the expression of TXNIP in islet P cells, improve islet P cell function, promote insulin synthesis and release, and improve insulin resistance and glucose metabolism disorder in diabetic mice." (PMID 34699301, 2021). "The outcome reveals, for the first time, a link of target pharmacology to insulin resistance, dysglycemia, blood pressure, dyslipidemia, and low-grade inflammation—including key mediators of insulin resistance, TXNIP, and TNFα." (PMID 34371884, 2021). "Akin to the effect of TXNIP on insulin resistance, the role of TXNIP in ischemic stroke showed exacerbated brain injury through redox imbalance and NLRP3 inflammasome activation." (PMID 31174550, 2019).
Insulin resistance (continued). "The TXNIP interaction is a specific feature of NLRP3, binding protein to the NLRP3 inflammasome, and is associated with insulin resistance and multiple organ damage." (PMID 31174550, 2019). "The increased SAT TXNIP DNA methylation in O-GDM disappeared after adjustment for the offspring ́s ambient insulin resistance (HOMA-IR), HbA1c levels and total body fat% (model 2, see Results section)." (PMID 29077742, 2017). "Knockdown of PTP1B, TXNIP, or other insulin resistance/apoptosis mediators." (PMID 41226304, 2025). "Indeed, Mondo A is also known to be a contributary factor to the development of insulin resistance through its increasing of the expression of thioredoxin interacting protein (TXNIP), impairment of insulin signaling, and increasing of lipogenesis." (PMID 35216280, 2022). "We then used a specific PI3K inhibitor, LY294002, to investigate whether RB ameliorates insulin resistance through the PI3K/AKT/TXNIP pathway in vitro." (PMID 35571083, 2022). "TXNIP is a mediator of insulin resistance in liver, skeletal muscle and adipose tissue, and impaired pancreatic beta-cell insulin secretion and TNFα decreases insulin receptor signaling in adipose tissue and skeletal muscle, particularly prior to development of T2DM." (PMID 34371884, 2021). "In addition, TXNIP is known to be one of the master regulators of metabolism, a well-established inhibitor of glucose uptake, mediator of insulin resistance, and is primarily involved in proper fatty acid utilization." (PMID 28661427, 2017). "Thus, TxNIP is also considered a key factor in the insulin resistance and can be induced in astrocytes, endothelial, and neuronal cells in vitro, by adding Aβ to the medium." (PMID 25815110, 2015). "The TxNIP gene appears elevated in insulin resistance/T2D and it is upregulated by glucose." (PMID 25815110, 2015). "Based on the pronounced insulin resistance observed in CS and low circulating OC levels, we hypothesized that long-term exposure to glucocorticoids could impact insulin resistance through TXNIP mediated mechanisms on OC in bone." (PMID 23691179, 2013). "Our data are suggesting that RAGE may induce brain insulin resistance by enhancing TXNIP expression." (PMID 22482078, 2012). "TXNIP is an intriguing candidate molecule that may provide a common link between brain insulin resistance and AD." (PMID 22482078, 2012). "From the hypothesized contribution of HK2-linked unscheduled glycolysis to the development of insulin resistance, the activation of the UPR provides a key contributory role, increasing the expression of established mediators of insulin resistance, TXNIP and tumor necrosis factor-α (TNFα)." (PMID 35216280, 2022). "Increased thioredoxin-interacting protein, which is thought to be an amplifier of oxidative stress and inflammasome activation and may mediate CNS insulin resistance, has been observed in AD patients with insulin resistance." (PMID 33920138, 2021). "Interestingly, both NLRP3 and TXNIP knockout mice have reduced insulin resistance." (PMID 28348460, 2017). "By inhibiting the TXNIP/NLRP3 pathways and improving autophagic clearance, transdermal application of Vera@CLCMP patches alleviated obesity-induced insulin resistance and hepatic steatosis." (PMID 36670488, 2023). "IRAK-M andmetabolic parameters, including fasting insulin (FINS), glycosylatedhemoglobin (HbA1c), homeostasis model assessment of insulin resistance(HOMA-IR) and beta-cell function (HOMA-β), and thioredoxin-interactingprotein (TXNIP), were evaluated." (PMID 36039603, 2022). "Further, NLRP3 can interact with thioredoxin-interacting protein (TXNIP), a protein involved in insulin resistance." (PMID 35428826, 2022). "In conclusion, our study shows that RB improves insulin resistance in vivo and in vitro, and the mechanism migh be through upregulating the PI3K/AKT signaling therefore suppressing TXNIP expression." (PMID 35571083, 2022).
Insulin resistance (continued). "The correction of insulin resistance by tRES-HESP in overweight and obese subjects in the HATFF study correlated with improvements in the expression of TXNIP and TNFα." (PMID 35216280, 2022). "Previous studies have shown that the binding of thioredoxin-interacting protein (TXNIP) to NLRP3 is significant for inflammasome activation and insulin resistance." (PMID 36422510, 2022). "The inhibition of the TXNIP/NLRP3 inflammasome pathway by miR-17 was confirmed in β cells of diabetic rats, brains of hypoxic-ischemic injured rats, and retinal Müller glial cells of mice after induction of high fat diet-induced insulin resistance." (PMID 39220230, 2024). "Moreover, thioredoxin-interacting protein (TXNIP), a protein connected to insulin resistance, interacted with NLRP3." (PMID 37859981, 2023). "In the present study, we showed that sustained transdermal delivery of verapamil via CLCMP-based patches could reduce insulin resistance and MAFLD by inhibiting the TXNIP/NLRP3 inflammasome pathway and improving autophagic degradation of protein aggregates." (PMID 36670488, 2023). "Thus, the protein expression of the insulin pathway inhibitors TXNIP and ARRDC4 decreased and improved insulin resistance and lipotoxicity." (PMID 36059548, 2022). "The reversal of insulin resistance induced by tRES-HESP was related inversely to expression of TNFα and TXNIP and may reflect countering of MG accumulation and protein glycation, with consequent decreased activation of the UPR." (PMID 34371884, 2021). "Accordingly, Alibegovic and colleagues in 2010 reported that physical inactivity insulin resistance is partly dependent on transcriptional changes inducing oxidative stress such as PPARGC1A and TXNIP (thioredoxin-interacting protein), in which daily physical activity reverses these changes." (PMID 34660812, 2021). "Furthermore, lower TXNIP levels directly inhibit the sparking of the NLRP3 inflammasome, an essential sensor that stimulates the production of pro-inflammatory cytokines like IL-1β that are connected to insulin resistance and β-cell mortality." (PMID 41300521, 2025). "Additionally, TXNIP is a key activator of the NLRP3 inflammasome, a complex that triggers the maturation and release of pro-inflammatory cytokines like IL-1β, which directly promote insulin resistance and β-cell damage." (PMID 41300521, 2025).
hepatocellular carcinoma (32 papers, 2013 to 2025). A malignant tumor that arises from hepatocytes. "As reported, TNXIP is a candidate tumor suppressor gene, and TXNIP-deficient mice are predisposed to hepatocellular carcinoma." (PMID 38789868, 2024). "In general, the promotion of cell proliferation is associated with carcinogenesis, and reduced TXNIP expression has been reported in several cancers, including hepatocellular carcinoma." (PMID 37141242, 2023). "Overexpression of TXNIP causes cell cycle arrest at the G1/S checkpoint in the hepatocellular carcinoma cell line HuH‐7." (PMID 30410860, 2018). "Furthermore, it has been demonstrated that the loss of TXNIP increases the predisposition to hepatocellular carcinoma; therefore, reactivating/inducing TXNIP expression is thought to be beneficial to anti-cancer therapy." (PMID 29534438, 2018). "However, another study, this time in HCC, observes that TXNIP expression is positively associated with the migratory and invasive ability of hepatocellular cancer cells, stressing the importance of underlying tissue and cell type in determining the impact of TXNIP function on migration." (PMID 37794178, 2023). "However, in line with our results a significantly increased expression of TXNIP and elevated ROS level was associated with invasive growth in human hepatocellular carcinoma and high expression of TXNIP was an independent prognostic factor in non-small lung cancer." (PMID 34433833, 2021). "For example, TXNIP-null mice exhibit a 40% higher incidence of hepatocellular carcinoma than wild-type (WT) mice." (PMID 40175348, 2025). "Vitamin D3 stimulates TXNIP expression in hepatocellular carcinoma and endometrial cancer cells, coupled with induction of apoptotic cell death and ROS production." (PMID 40175348, 2025). "The study identifies PIAS3 as a key promoter of ferroptosis in hepatocellular carcinoma (HCC) by regulating TXNIP through TGF-β signaling, suggesting a novel therapeutic target for enhancing ferroptotic sensitivity in HCC treatment." (PMID 39315094, 2024). "After D-allose-induced TXNIP up-regulation in hepatocellular carcinoma was revealed by microarray analysis, it was reported in various cancers, including in this study." (PMID 35743212, 2022). "TXNIP deficit is adequate for explaining hepatocellular carcinoma (HCC), which points to new pathways for how HCC develops." (PMID 36366411, 2022). "TXNIP activates the expression of oncogenes to inhibit the proliferation of hepatocellular carcinoma cells and induces apoptosis." (PMID 34603396, 2021). "TXNIP expression in vitro inhibited hepatocellular carcinoma cell proliferation and induced apoptosis." (PMID 33203882, 2020). "It has been found that heparin influences cell growth, differentiation, invasion, and migration and promotes the transcription of TXNIP in hepatoma cells by binding to the ChoRE-b site." (PMID 33194655, 2020). "Altered TXNIP mRNA expression was previously reported following CD47 knockdown in hepatocellular carcinoma stem cells." (PMID 26840086, 2016). "Furthermore, TXNIP mediates acetylation inhibitor-induced suppression of hepatocellular carcinoma by triggering potassium deprivation." (PMID 40182050, 2025). "In addition, studies have shown that TXNIP expression is downregulated in other tumors such as hepatocellular carcinoma, lung cancer and bladder cancer." (PMID 38244591, 2024). "Additionally, through mitochondria-mediated ROS production and activation of MAPK pathways, TXNIP overexpression inhibited hepatocellular carcinoma cell proliferation." (PMID 37032654, 2023). "Indeed, TXNIP was found to be downregulated in hepatocellular carcinoma (HCC) in a majority of patients." (PMID 33081035, 2020). "However, it has also been reported that TXNIP overexpression inhibits proliferation and the induction of apoptosis in hepatoma cells by triggering the mitochondrial-mediated production of ROS and activation of the MAPK pathway." (PMID 33194655, 2020).
hepatocellular carcinoma (continued). "In cancer, TXNIP was initially considered a tumor suppressor, this being notably supported by the observation that TXNIP-deficient mice exhibit a 40% higher incidence of spontaneously developing hepatocellular carcinoma." (PMID 40260243, 2025). "For instance, in hepatocellular carcinoma (HCC) and renal clear cell carcinoma, the overexpression of TXNIP promotes angiogenesis and the spread of cancer cells." (PMID 40182050, 2025). "Moreover, hepatocellular carcinoma (HCC)–derived EVs are abundant with miR–3129, which promotes the growth and metastasis of HCC via targeting TXNIP." (PMID 37835573, 2023). "Our study indicates that the TXNIP-FOXO axis contributes to cell cycle arrest and is important for MK-801-mediated hepatocellular carcinoma growth inhibition." (PMID 24112473, 2013). "A study showed that TXNIP expression in human hepatocellular carcinoma (HCC) specimens and HCC-derived cell lines is low or absent." (PMID 35450411, 2022). "A mouse strain with a spontaneous nonsense mutation in TXNIP has dramatically increased incidence of spontaneous hepatocellular carcinomas (HCC), and TXNIP-knockout mice develop increased number and size of HCC in a diethylnitrosamine (DEN)-induced murine model of HCC." (PMID 24645981, 2014). "Some studies have shown that TXNIP expression levels in hepatoma cell lines are low or absent." (PMID 33194655, 2020).